YWHAZ (tyrosine 3-monooxygenase/tryptophan 5-monooxygenase activation protein zeta)
Diseases named in the same sentence as YWHAZ in open-access papers (continued):
Sharing a sentence is not in itself a finding about the gene and the disease.
infection (9 papers, 2015 to 2024). The state of being infected such as from the introduction of a foreign agent such as serum, vaccine, antigenic substance or organism. "Taken together, these results suggested that infection of H. pylori was associated with higher miR-193a methylation and YWHAZ expression, probably due to activation of JAK/STAT signaling." (PMID 33718136, 2021). "The results showed that GZ7/cagA infection decreased YWHAZ expression, which is consistent with the observed reduction in YWHAZ expression in cells overexpressing H19." (PMID 38902391, 2024). "On days 6, 10, and 11 post-infection (equivalent to days 15, 19, and 20 of egg incubation), qRT-PCR showed that the YWHAZ expression levels were significantly lower in the lungs of the MG-infected chicken embryos compared with the control." (PMID 29652844, 2018). "To further verify the role of YWHAZ in MG-HS infection, we detected the expression of YWHAZ in MG-HS-infected chicken embryos and DF-1 cells." (PMID 29652844, 2018). "Interestingly, GZ7/cagA infection counteracted the upregulation of YWHAZ expression induced by si-H19." (PMID 38902391, 2024). "GZ7/cagA infection responded to the increased YWHAZ expression induced by H19 knockdown." (PMID 38902391, 2024). "In contrast, YWHAZ expression was upregulated in H19 knockdown cells, and GZ7/cagA infection could respond to the high YWHAZ expression caused by H19 knockdown." (PMID 38902391, 2024). "In conclusion, GAPDH and YWHAZ could be used as reference genes for the normalisation of chicken IEL-NK cell gene responses to infection with vvIBDV." (PMID 32444639, 2020). "Moreover, we found AhR and Arnt were up-regulated in MG-HS infection, and AhR:Arnt decreased YWHAZ (14-3-3ζ ) expression probably through regulating gga-miR-451." (PMID 31238581, 2019). "However, infection with GZ7/cagA decreased the expression of YWHAZ." (PMID 38902391, 2024). "Thus, GAPDH and YWHAZ could be used as reference genes for the normalisation of chicken IEL-NK cell gene response following infection with vvIBDV, whereas the commonly used ACTB is unsuitable to be used as a reference gene in IEL-NK cells infected with vvIBDV." (PMID 32444639, 2020). "In order to confirm the interaction between gga-miR-451 and YWHAZ in DF-1 cells, we detected YWHAZ expression after miRNA transfection or different virulence NDV strains infection using Western Blot." (PMID 31396181, 2019).
neurodegenerative disease (4 papers, 2019 to 2025). A disorder of the central nervous system characterized by gradual and progressive loss of neural tissue and neurologic function. "The prioritized genes and pathways, particularly the YWHAZ neuronal-glial axis and the Ecdysterone-COX6B1 interaction, represent compelling targets for future research aimed at developing novel interventions for neurodegenerative diseases." (PMID 41296471, 2025).
respiratory diseases (3 papers, 2012 to 2020). "Since in the most cases, Gram-negative and Gram-positive bacteria are observed together in respiratory diseases, HPRT1, YWHAZ and SDHA might be an appropriate set of reference genes for the gene expression normalization in AM studies." (PMID 22340302, 2012).
neurodevelopmental disorder (1 paper, 2020). A behavioral and cognitive disorder with onset during the developmental period that involves impaired or aberrant development of intellectual, motor, or social functions. "Altogether, these findings support an essential role for the YWHAZ gene in brain function and development, and together with our current report, highlight its contribution to neurodevelopmental disorders." (PMID 32545830, 2020). "Several studies have demonstrated the role of YWHAZ and other family members in neurogenesis and neurodifferentiation, and its possible implication in neurodevelopmental disorders." (PMID 32545830, 2020).
neurological diseases (1 paper, 2023). "Among the top 50 database-predicted targeted genes, 8 genes (HOMER1, FRAT2, GRM5, TGFBR1, KDM3A, RGS2, ARRB1, and YWHAZ) were reported to be associated with axonal/neuronal regeneration/or neurological diseases." (PMID 36959678, 2023).
YWHAZ also shares sentences with these, for which no sentence is quoted: non-small cell lung carcinoma (6 papers); colon adenocarcinoma (2); glioblastoma (2); goiter (2); Intellectual disability (2); intrahepatic cholangiocarcinoma (2); lymphoma (2); oral squamous cell carcinoma (2); osteosarcoma (2); pancreatic ductal adenocarcinoma (2); polycystic ovarian syndrome (2); psychiatric disorder (2); acute myeloid leukemia (1); adenocarcinoma of the esophagogastric junction (1); amyotrophic lateral sclerosis (1); Autoimmunity (1); B cell lymphomas (1); basal cell carcinoma (1); breast tumors (1); cardiofaciocutaneous syndrome (1); celiac disease (1); chronic hepatitis (1); chronic pancreatitis (1); depression (1); diffuse large B-cell lymphoma (1); endometrial adenocarcinoma (1); esophageal cancer (1); esophageal squamous cell carcinoma (1); esophagus carcinoma (1); Fabry disease (1).
A further 27 diseases each share a sentence with YWHAZ in 1 paper.